INS (insulin)
Diseases named in the same sentence as INS in open-access papers (continued):
Sharing a sentence is not in itself a finding about the gene and the disease.
Hypercholesterolemia (continued). "leaves evaluated in rats with hypercholesterolemia, using a dose of 10 mg/kg, indicated a glucose reduction of 16% (aqueous extract) and 11% (methanolic extract), possibly due to an increase in insulin secretion." (PMID 37432178, 2023). "In vitro assays suggest hypercholesterolemia could promote islet dysfunction, modifying insulin secretion." (PMID 36005626, 2022). "Glucose/insulin promotes cholesterol biosynthesis and cholesterol uptake, which indicates that drugs targeting lowering glucose may help to control hypercholesterolemia." (PMID 35571202, 2022). "In this line, CoQ10 has shown pain-alleviating properties in fibromyalgia patients, a membrane-stabilizing function, immune system enhancing ability, or a fundamental role for insulin sensitivity, apart from potentially beneficial properties for familial hypercholesterolemia patients." (PMID 33182646, 2020). "There is numerous evidence that hypercholesterolemia itself could deteriorate glucose-stimulated insulin secretion and insulin sensitivity." (PMID 28545051, 2017). "HF mice showed hypercholesterolemia and decreased insulin sensitivity as also previously shown." (PMID 25332517, 2014). "Thus, cholesterol accumulation alters beta cell functions and insulin secretion, as well as insulin-stimulated cholesterol biosynthesis, and controls its circulating levels, which form a strong bond between hypercholesterolemia and T2DM." (PMID 25346723, 2014). "Interestingly, in parallel to total NO metabolite alteration, the hypercholesterolemia induced insulin increment in rabbits." (PMID 23497719, 2012). "We aimed at identifying in the present study whether the coactivator of insulin transcription PSMD9 may contribute to linkage to hypercholesterolemia in 200 Italian T2D families." (PMID 21554682, 2011). "Insulin is a lipid-synthetic hormone, thus alteration in a gene regulating insulin gene transcription may alter lipid metabolism as well and contribute to hypercholesterolemia." (PMID 21554682, 2011). "In addition, evidence suggests that hypercholesterolemia itself could reduce glucose-stimulated insulin secretion and insulin sensitivity, which agrees with the reduced ability to secrete insulin as observed in NTG T2D-Control mice in our study." (PMID 38763496, 2024). "Although not fully understood, glucose metabolism, insulin signaling, impairment of amyloid clearance capacity, hypercholesterolemia, vascular defect, oxidative stress, and chronic inflammation may account for the association between T2DM and cognitive impairment." (PMID 28951620, 2017). "Additionally, insulin lack is connected with hypercholesterolemia." (PMID 25114914, 2014). "The observation of higher glucose levels despite greater insulin release suggests that older control females develop some degree of IR even on regular chow, and that nLDL-immunization is protective even under conditions of euglycemia (and moderate spontaneous hypercholesterolemia)." (PMID 23028961, 2012). "Insulin stimulates the production of the LDL receptors, thus, hypercholesterolemia appears to be primarily the result of a decrease in receptor-mediated uptake of LDL." (PMID 40033334, 2025). "We have previously shown that Swiss mice are responsive to the HF/HS diet, leading to an increase in weight gain, including hypercholesterolemia, and altered serum glucose (GTT) and insulin tolerance (ITT) after 7 weeks of feeding." (PMID 38585221, 2024). "Insulin inhibits HMG-CoA reductase, an enzyme that catalyzes the rate-limiting step in cholesterol synthesis, resulting in hypercholesterolemia." (PMID 35308202, 2022). "We examined alteration of plasma levels of insulin, C-reactive protein (CRP) and total NO metabolites (NOx), as well as fatty streak formation in the rabbit model of hypercholesterolemia." (PMID 23497719, 2012).
Hypercholesterolemia (continued). "On the other hand, Ces2–/– mice exhibited fatty liver, adipositis, hypercholesterolemia and diminished glucose tolerance and insulin sensitivity, but without body mass changes." (PMID 39496863, 2025). "Fourth, diet therapy and exercise therapy are recommended when BMI begins to increase, and medications for hypercholesterolemia such as hydroxymethylglutaryl-coenzyme A reductase inhibitors and those for DM such as SGLT2 and insulin should be utilized for metabolic abnormalities." (PMID 39693239, 2025). "Plasma insulin levels did not change in response to isolated hypercholesterolemia suggesting an intact endocrine function of the pancreas." (PMID 28750643, 2017). "This points to the important fact that the insulin resistance along with hypercholesterolemia can be independent of the fat intake." (PMID 28432486, 2017). "Therefore in this study we examined plasma levels of insulin, C-reactive protein (CRP) and total NO metabolites (NOx), as well as fatty streak formation in the rabbit model of hypercholesterolemia." (PMID 23497719, 2012). "In atherosclerotic arteries negative or inadequate remodeling is more common in insulin-using than non-insulin-using diabetics, more common in smokers compared with nonsmokers, and less frequent in patients with hypercholesterolaemia." (PMID 15268762, 2004). "However, the role of UPR in LDL-hypercholesterolemia and the impact on intracellular cholesterol and insulin metabolism in β-cells has not been elucidated." (PMID 36005626, 2022). "However, metabolic disorders such as impaired insulin sensitivity, hypercholesterolemia, and liver steatosis are often diagnosed even in non-obese ones." (PMID 28397183, 2017).
macrosomia (170 papers, 2007 to 2026). "It has been noted that glyburide increases the risk for macrosomia by 2-fold compared to insulin therapy and raised concerns that transplacental glyburide and fetal exposure were possible mechanisms underlying this outcome." (PMID 40137145, 2025). "A multivariate model further demonstrated a strong association between SAF values and macrosomia after adjusting for insulin status (OR: 4.32; 95% CI: 1.52–12.30)." (PMID 40243644, 2025). "A genetically unaffected foetus of a woman with a GCK mutation is 600 g heavier at birth with a higher risk of foetal macrosomia due to dysregulated insulin stimulated foetal growth." (PMID 38933924, 2024). "Persistently elevated maternal blood glucose also affects the developing fetus, causing excessive production of fetal insulin, resulting in a higher incidence of macrosomia and birth trauma." (PMID 38612572, 2024). "Similar to the birth weight in the metformin-exposed group, metformin also lowered the risk of macrosomia by 30% compared with the insulin-exposed group based on 20 studies (RR 0.75; 95% CI 0.54, 0.86; I2 = 17%; p = 0.001)." (PMID 36593391, 2023). "Among participating mother-neonate dyad, maternal BMI at birth, neonate’s gender, and fetal cord serum IGF-1, and serum insulin were significantly associated with fetal macrosomia." (PMID 36001625, 2022). "Among participating mother-neonate dyad, maternal BMI at birth, neonate’s gender, and fetal cord serum IGF-1 and serum insulin are significantly associated with fetal macrosomia." (PMID 36001625, 2022). "Pedersen suggested that the transfer of excess maternal glucose stimulated the fetal islets, raising insulin levels and, as a consequence, increasing fetal glucose consumption and the risk of macrosomia." (PMID 36014853, 2022). "A review of the dietary interventions for GDM showed that a low-GI diet characterized by the intake of high-quality complex CHO can reduce insulin utilization and the risk of macrosomia." (PMID 35057540, 2022). "Previous randomized controlled trials also implied that glycemic control through dietary intervention, physical activity, and/or insulin therapy was able to reduce the risk of macrosomia and LGA." (PMID 34113682, 2021). "Hyperinsulinemia and glucose excess in utero cause insulin-sensitive tissue hypertrophy, promoting accelerated growth that can lead to macrosomia and/or large-for-gestational-age (LGA) neonates." (PMID 33939909, 2021). "Glucose passes through the placenta to the foetus and increases foetal insulin production, which, in turn, stimulates foetal growth, causing macrosomia and children large for gestational age (LGA)." (PMID 33036170, 2020). "By contrast, infants with a PI ≥ 97th percentile have asymmetric macrosomia associated with a higher fat mass, and cord blood insulin and leptin levels." (PMID 32346630, 2020). "Glyburide-exposed neonates were heavier at birth (58.20 g, 95% confidence interval [CI] 10.10–106.31, p = 0.02) with increased risk of macrosomia (odds ratio [OR] 1.38, 95% CI 1.01–1.89, p = 0.04) versus neonates of insulin-treated mothers." (PMID 32442232, 2020). "Metformin-exposed neonates were born lighter (−73.92 g, 95% CI −114.79 to −33.06 g, p < 0.001) with reduced risk of macrosomia (OR 0.60, 95% CI 0.45–0.79, p < 0.001) than insulin-exposed neonates." (PMID 32442232, 2020). "The overall lower incidence of macrosomia and the average lower birth weight associated with metformin compared to insulin treatment in trial contexts has been interpreted as evidence of efficacy and beneficial impact on fetal growth." (PMID 31386659, 2019). "Compared with metformin, insulin had a significant increase in the gestational age at delivery (MD, 0.23; 95% CI, 0.12 to 0.34; P < 0.001); likewise, insulin had a risk of macrosomia (RR, 0.68; 95% CI, 0.55 to 0.86; P < 0.05)." (PMID 31781670, 2019). "High levels of insulin circulating through the body of a fetus causes a stimulation of growth known as macrosomia." (PMID 31647034, 2019).
macrosomia (continued). "Risk of macrosomia appeared higher in patients receiving glyburide than in those receiving insulin [RR, 2.48; 95%CI, 1.38 to 4.44; p = 0.002], with I2 decreasing from 66% to 30%." (PMID 28771572, 2017). "Studies have shown that insulin analogs (lispro and aspart) are more effective than regular human insulin in achieving targeted glucose values and minimizing the risk for macrosomia." (PMID 25977899, 2015). "Given the association between mTOR signaling and fetal overgrowth, further research is needed to determine whether modifying treatment strategies could mitigate macrosomia risk in insulin-treated GDM pregnancies." (PMID 40136665, 2025). "However, one study reported that AF insulin is significantly associated with the risk of macrosomia among women with a positive glucose challenge test." (PMID 39599591, 2024). "Some factors were associated with worse outcomes: high pregestational BMI was associated with higher risk of preeclampsia and macrosomia, while more than recommended weight gain was only associated with macrosomia; use of insulin decreased the risk of preeclampsia." (PMID 36419098, 2022). "After multivariable analysis that corrected for confounding factors, maternal BMI at birth (P-value < 0.001), fetal gender (P-value = 0.001), fetal cord serum IGF -1 (P-value = 0.002), and insulin assay (P-value = 0.034) were significantly associated with fetal macrosomia." (PMID 36001625, 2022). "Glyburide has been reported to be associated with a higher rate of neonatal hypoglycemia and macrosomia than insulin or metformin although metformin may lead to nutrient restriction of glucose and amino acids to the fetus." (PMID 34579668, 2021). "The hypothesis of reducing the risk of fetal macrosomia is that physical activity during pregnancy could reduce fetal fat mass by increasing insulin sensitivity and by modulating glucose regulation." (PMID 32182850, 2020). "Indeed, newborn babies are at risk of macrosomia (large-for-gestational age) as a result of insulin and insulin-like growth factors that together stimulate fetal growth." (PMID 29621322, 2018). "Insulin therapy decreases the frequency of fetal macrosomia and the risk of perinatal morbidity." (PMID 25977899, 2015). "A meta-analysis study on the use of glibenclamide in GDM women found the drug to be as effective as insulin therapy however the risk of developing neonatal hypoglycemia, high fetal birth weight, and macrosomia were increased in women treated with glibenclamide." (PMID 25849717, 2015). "Earlier studies have shown that insulin–antibody complexes may cross the placenta and be associated with the development of macrosomia in the infant." (PMID 17888133, 2007). "Moreover, occurrence of macrosomia increased with the HOMA-IR group, indicating that a pregestational insulin signaling disturbance might be associated with the risk of macrosomia in neonates." (PMID 35784578, 2022). "However, when insulin therapy had to be initiated in at risk pregnancies, strict blood glucose targets (4.4 and 6.1 mmol/L, 80 and 110 mg/dl, fasting and after meals, respectively) were set to reduce the risk of macrosomia." (PMID 35069449, 2021). "Understanding certain modifiable risk factors for macrosomia such as high pre-pregnancy body mass index, high blood glucose level during pregnancy and low level of pre-gestational physical activity are crucial for health care providers to prevent macrosomia by suitable diet and insulin therapy." (PMID 30545390, 2018). "However, further increases in insulin resistance in the gestational period may cause abnormal fetal growth, fetal macrosomia and IUGR." (PMID 29809159, 2018). "The rates of insulin use during pregnancy, preterm birth, low birth weight, and macrosomia were 41.1%,10.7%, 6.9%, and 7.6%, respectively." (PMID 40871628, 2025).
macrosomia (continued). "This excess of blood sugar and insulin can result in increased fat and protein synthesis in the fetus, often manifesting as macrosomia, which is characterized by an enlarged upper body." (PMID 41142499, 2025). "Conversely, foetal overnutrition can drive excessive insulin secretion and fat accretion, resulting in macrosomia." (PMID 40218968, 2025). "In one study GCK unaffected offspring whose mothers were treated with insulin had a lower rate of macrosomia compared to the non-insulin treated group (33.3% vs. 62.5%)." (PMID 38933924, 2024). "The trend of increasing aOR with escalating glucose categories was still observed for any complications, maternal insulin use, shoulder dystocia, macrosomia, and LGA." (PMID 39448754, 2024). "Categorical analysis found that the aOR for any complications, maternal insulin use, shoulder dystocia, macrosomia, and LGA increased with escalating FG levels." (PMID 39448754, 2024). "The primary outcomes were maternal glucose control, birth weight of newborns, macrosomia and preterm birth rate, and rate of need for insulin therapy." (PMID 39481539, 2024). "It is also uncertain what the contributions of IGF-1 and insulin are to fetal macrosomia in this setting." (PMID 36001625, 2022). "Low-carbohydrate diets significantly reduce postprandial glucose levels and improve pregnancy outcomes by reducing the incidence of macrosomia-related caesarean sections and the requirement for insulin therapy." (PMID 35745174, 2022). "The conventional wisdom is that this is the cause of macrosomia in GDM pregnancies because the foetus is hyperinsulinaemic and the insulin resistance of the mother drives glucose and lipids across the placenta." (PMID 35475555, 2022). "The metformin group had significant lower birth weight and a lower prevalence of macrosomia than the insulin group." (PMID 34641848, 2021). "These recommendations mainly apply to the use of insulin therapy to prevent macrosomia and its potential consequences reviewed in." (PMID 35069449, 2021). "Pairwise meta-analysis of macrosomia showed a lower prevalence in the metformin group than in the insulin group (RD − 0.03; 95% CI − 0.06, 0), but the difference was not significant (p = 0.09)." (PMID 34641848, 2021). "In 10 studies including 1,810 women, metformin-exposed neonates had reduced rates of macrosomia compared to insulin-exposed neonates (OR 0.60, 95% CI 0.45 to 0.79, I2 = 5%, p < 0.001)." (PMID 32442232, 2020). "Our results demonstrate that babies exposed to glyburide are significantly heavier at birth and have increased incidence of macrosomia compared to those whose mothers were randomised to insulin." (PMID 32442232, 2020). "In seven studies including 1,587 participants, neonates exposed to glyburide had increased rates of macrosomia compared to insulin-exposed neonates (OR 1.38, 95% CI 1.01 to 1.89; I2 = 31%, p = 0.04)." (PMID 32442232, 2020). "It is possible that early diagnosis with IADPSG criteria allowed for a longer time frame to achieve normoglycemia via multidisciplinary care and insulin as required, thereby reducing the frequency of macrosomia to that found in Late GDM." (PMID 32411467, 2020). "Conversely, metformin-exposed babies are significantly lighter at birth and have reduced incidence of macrosomia compared to insulin-exposed babies." (PMID 32442232, 2020). "The contemporary evidence in non-insulin treated GDM patients from Iran suggests that antenatal vitamin D containing supplements decreases the risk of CS and macrosomia, compared to placebo." (PMID 32517428, 2020). "Macrosomia was included as an outcome between metformin and insulin by 13 studies which involved 2331 GDM patients." (PMID 31781670, 2019). "Nine studies involving 2227 GDM patients focused on the incidence of macrosomia between glyburide and insulin." (PMID 31781670, 2019). "Obese women with GDM who achieved desired levels of glycemic control using insulin therapy had similar macrosomia rates to normal-weight controls." (PMID 31278325, 2019).